FASN (fatty acid synthase)
Diseases named in the same sentence as FASN in open-access papers (continued):
Sharing a sentence is not in itself a finding about the gene and the disease.
tumor (continued). "Taken together, FASN can contribute to the TME formation and tumor immune response." (PMID 38272906, 2024). "Taken together, we could conclude that the inhibitory impact of FASN on ferroptosis was achieved via NF-κB/STAT3/GPX4 axis, thereby facilitating tumor growth and resistance to ADM in DLBCL." (PMID 39345091, 2024). "Furthermore, the overexpression of FASN resulted in the upregulation of GPX4 and the downregulation of 4-HNE in tumor tissues, indicating an inhibition of ferroptosis." (PMID 39345091, 2024). "Furthermore, we examined the expression levels of ACADM, FASN, ACC1, ELOVL5, and FABP1 in primary tumor tissues and TD tissues through IHC methods." (PMID 39495391, 2024). "Taken together, our results not only reveal a novel biological function of ZDHHC21 as a tumor suppressor in DLBCL and identify it as a key regulator for FASN palmitoylation for the first time but also establish targeting ZDHHC21/FASN axis as a promising therapeutic strategy for patients with DLBCL." (PMID 38195819, 2024). "In cisplatin-resistant NSCLC cells, cerulenin reduced the metastatic potential by targeting the EMT regulated by FASN, without any impact on tumour growth, which was confirmed in an orthotropic model." (PMID 38610991, 2024). "Coincident with the performance in ICC cell lines, compared to adjacent non-tumor tissues, the RNA level of FASN was not significantly different between ICC tissues and normal tissues adjacent to ICC tissues." (PMID 36635270, 2023). "Ventura and colleagues proposed that pharmacological inhibition of FASN with TVB-3166 reduces cell proliferation and xenograft tumor growth of KRAS mutated NSCLC, but not CRC cell lines via, at least in part, inhibition of the PI3K–AKT–mTOR pathway." (PMID 36675307, 2023). "Furthermore, enhanced activities of lipogenic enzymes ACC and FASN, as well as a comparable activity of lipid catabolic CPT1, were observed in tumor spheres, indicating an enhanced lipogenesis and an unchanged lipid catabolism in NSCLC CSCs." (PMID 36809297, 2023). "ATP citric acid lyase (ACLY), fatty acid synthase (FASN), acetyl-CoA carboxylase (ACC), and acetyl-CoA (Ac CoA) are indispensable enzymes in lipid metabolism, which influence the metabolism of immune cells and tumor cells." (PMID 38264667, 2023). "Interestingly, APOA1, FASN, FABP4, and LPL were oppositely dysregulated in liver and lung metastasis compared to the primary CRC tumour, whereas AGPAT1 was found to be significantly upregulated in lung metastasis." (PMID 35957902, 2022). "Interestingly, despite the potent impact of FASN inhibitors on cell viability, we found that Orlistat elicited an increase in FASN expression, which led us to hypothesize that this could be triggered by a feedback mechanism because of high metabolic flexibilities in tumour cells." (PMID 36139650, 2022). "The upregulation of FASN enhances lipogenesis in tumor cells, mainly through activation of the AKT/mTOR signaling pathway, thereby contributing to the immunometabolic switch in the tumor microenvironment and enhancing tumor growth and proliferation." (PMID 35127296, 2022). "Indeed, there has been considerable interest in the development of FASN inhibitors, which include the next‐generation therapeutics such as TVB‐2640 and yields high anti‐tumor potential and limited systematic toxicity in clinical trials." (PMID 36028991, 2022). "Furthermore, several biological experimental models have established the idea that elimination of FASN delays the tumorigenesis of HCC and prevents tumor proliferation." (PMID 36330335, 2022).
tumor (continued). "One study looked at several TNBC cell lines (including developed doxorubicin-resistant TNBC cell lines) and 29 primary tumours and reported the overexpression of fatty acid synthase (FASN) in TNBC; with FASN inhibitors being used as adjuvants to achieve significant therapeutic benefits." (PMID 36290817, 2022). "Even though multiple studies demonstrate that inhibition of FASN decreases CRC cell growth and survival in vitro, pre-clinical studies demonstrate much less efficacy of FASN inhibition on tumor growth in vivo, potentially due to compensation mechanisms such as dietary fatty acid uptake." (PMID 35742953, 2022). "By inhibiting FASN and stearyl CoA desaturase 1 (SCD1)–mediated lipid synthesis, miR-4310 inhibited HCC cell proliferation, migration, and invasion in vitro and inhibited HCC tumor growth and metastasis in vivo." (PMID 36452489, 2022). "The results demonstrated that the overall trend of FASN expression was increased in CESC (p < 0.05), KIRC (p < 0.01), and UCEC (p < 0.001) with increasing tumor malignancy (i.e., lower tumor differentiation), but decreased in HNSC and LGG (p < 0.001), decreasing with tumor progression." (PMID 36555243, 2022). "Although TVB‐3166 is a highly selective FASN inhibitor, it fails to suppress FASN expression in tumor cell line xenografts, and ACC phosphorylation is most likely one of the key causes." (PMID 35243817, 2022). "In terms of combination therapies, FASN inhibition with TVB-3166 or TVB-3664 could inhibit tubulin palmitoylation and show stronger anti-tumor effects with the combination of taxane drugs." (PMID 36172157, 2022). "Recent examples include knockdown of ACLY impairing pancreatic tumor formation and knockdown of FASN blocking tumor development in mTOR-driven liver cancer, while pharmacological inhibition of FAS reduced tumor growth in preclinical models of castration-resistant prostate cancer." (PMID 33413672, 2021). "In our previous study, orlistat could improve radiotherapy outcomes in both LNCaP cells and PC3 cells via inhibiting FASN activity and phosphorylation of AKT pathway in vitro and reduce the tumor volume in vivo." (PMID 33974005, 2021). "In this context, fatty acid synthase (FASN) is a rate-limiting enzyme in this process, and several FASN inhibitors, including TVB-3166 and TVB-2640, suppressed tumor growth by 15% in 22Rv1 xenografts, and notably, induced up to 97% tumor growth inhibition in combination with paclitaxel." (PMID 35127483, 2021). "Indeed, we have observed that ASO-LINC00842, which inhibits LINC00842, or Orlistat, which inhibits FASN activity, and combination of these two agents can significantly and synergistically repress PDAC growth and tumor burden in mouse xenograft and PDX models." (PMID 34158490, 2021). "In addition the levels of Ki67, indicating proliferating cells, and downstream effector of PPARG, FASN, were also similar to NTS control in these tumours, with FASN expression levels correlating with PPARG." (PMID 33654198, 2021). "In addition, we validated (i) the co-regulatory feedback loop between SREBF1/TP63/KLF5, and (ii) canonical target genes of SREBF1 in fatty-acid metabolism (e.g., ACLY, FASN, and SCD) in xenograft tumor samples." (PMID 34272396, 2021). "While mechanistic insights explaining this paradox are not fully explained, the role of fatty acid synthase (FASN) in tumor cells and role of peritumor adipose tissue and inflammation were reported." (PMID 33803184, 2021). "Furthermore, LINC00842 RNA levels as well as YY1, FASN, and acetylated PGC-1α protein levels were significantly and positively correlated with each other in PDAC tumor and normal tissues." (PMID 34158490, 2021). "Hypoxia-activated HIF-1α enhances lactate acidosis in the tumor microenvironment, and dysregulated pH in the tumor microenvironment activates SREBP-1c and FASN expression to speed up the fatty acid synthesis required for plasma membrane synthesis in rapidly proliferating cells." (PMID 34869321, 2021).
tumor (continued). "It has been found that a variety of enzymes involved in lipid anabolism and catabolism are related to tumor metastasis, including adenosine triphosphate (ATP) citrate lyase (ACLY), fatty‐acid synthase (FASN), stearoyl‐CoA desaturases (SCD), and monoacylglycerol lipases." (PMID 34977870, 2021). "Our results distinguished FASN, FN, TFRC and TSC1 from previously identified tumour promoters and revealed novel prediction model IPRPs that outperformed the currently established prognostic parameters for anticipating disease course and better clinical management of adult ACC." (PMID 33626208, 2021). "Indeed, tumor cells often overexpress acetyl-CoA carboxylase (ACACA), ATP citrate lyase (ACLY), and fatty acid synthase (FASN), key enzymes responsible for de novo biosynthesis of fatty acids, which makes them attractive targets for therapeutic interventions." (PMID 34206240, 2021). "FASN may bind to SPTBN1 and CD59 to mediate invasion and migration in tumor cells, and regulate the activation of the TGF-β-induced EMT." (PMID 32699531, 2020). "Targeting FASN may be helpful for the treatment of human HCC, at least in the tumor subset displaying c-MYC amplification or activation." (PMID 33187130, 2020). "Notably, CAFs display higher FASN activity and serve as hubs to supplement fatty acids for TNBC tumor cells." (PMID 32296646, 2020). "It was reported that 92 % of tumor samples derived from 100 TNBC patients expressed FASN and that doxorubicin-resistant cell lines were sensitive to chemotherapeutic drugs through inhibition of FASN." (PMID 33015128, 2020). "Our previous studies demonstrate that the effect of FASN inhibition on cellular proliferation in vitro does not always translate to the same effect on tumor growth in vivo." (PMID 32850342, 2020). "In rapidly proliferating tumor cells, the de novo synthesis of fatty acid is enhanced and the expression of key fatty acid synthesis enzymes, including acetyl CoA carboxylase (ACC) and fatty acid synthase (FASN), is increased." (PMID 33604287, 2020). "The literature indicates that FASN promotes the proliferation, invasion and migration of tumor cells by interacting with various molecules, including nonstructural protein 5B and caveolin-1." (PMID 32699531, 2020). "Based on these encouraging data and in the light of the problems in directly targeting the c-MYC protooncogene, the use of FASN inhibitors might represent a valid therapeutic approach for HCC, at least in the tumor subset showing activation of c-MYC." (PMID 33187130, 2020). "Tumors were histopathologically identical to those developed in c-Myc/MCL1 mice, implying that the absence of FASN does not modify the tumor phenotype in this mouse model." (PMID 33187130, 2020). "These two important antitumor properties may be mediated by the abrogation of FASN and CD44 pro-tumor activity." (PMID 31936544, 2020). "The staining of FASN in tumor tissue was significantly stronger than in paracancerous normal tissue (p < 0.001)." (PMID 32655718, 2020). "Indeed, we found that inhibition of FASN selectively upregulates CD36 mRNA and protein expression, but not expression of other FA transporters in multiple models including CRC cells, tumor xenografts, genetically modified mice and in human tissues." (PMID 32850342, 2020). "In addition, we found expression of these three molecules (FASN/ERK1/2/Bcl-xL) were consistent and increased simultaneously in tumor cells." (PMID 30931932, 2019). "Last, tumor epithelial cells from the breast of PyMT animals with (FASN+/+; PyMT) or without (FASN∆/∆; PyMT) FASN displayed similar intracellular neutral lipid accumulation evidenced by oil-red staining." (PMID 31676791, 2019). "We found that SR9243 downregulated the lipogenesis genes SREBP-1c, FASN and SCD1, which reduced the intracellular FA content to exert a tumour suppressor effect, and that ccRCC cells could exogenously take up FAs to rescue tumour death." (PMID 31138790, 2019).
tumor (continued). "Finally, when HC11 cells with CRISPR-deleted FASN were infected with PyMT or KRAS and grafted into wild-type animals, a delay on tumor onset was observed compared with wild-type counterparts." (PMID 31676791, 2019). "Compared to FASN-overexpressing cells, knockdown of FABP5 in FASN-overexpressing cells (FASN/shFABP5) significantly reduced luciferase signal in the primary tumor, whole mouse, and femurs in vivo, confirming that FABP5 knockdown suppresses the ability of FASN to promote metastasis." (PMID 31831821, 2019). "In conclusion, our study suggests that AKT1, PRDM10, and FASN may be tumour promoters and that FLNA may be a tumour suppressor in PCa." (PMID 30872976, 2019). "Moreover, treatment of tumor cells with the LXR agonist GW3965 counteracted LD accumulation, whereas a FASN inhibitor increased LD levels." (PMID 31835444, 2019). "Despite its significant roles in tumor growth and metastasis, FASN inhibitors have not yet been investigated in clinical trials." (PMID 31027222, 2019). "In addition, knockdown of SREBP1, the major regulator of lipogenesis which controls the expression of FASN and SCD1, efficiently inhibited tumor growth." (PMID 29552293, 2018). "Treatment of CRC PDXs with TVB-3664 as a monotherapy led to a significant decrease in tumor volume in 30% of cases suggesting that the presence of FASN expression does not predict response to FASN inhibitors." (PMID 29872506, 2018). "To directly address this function of TIDCs, we sorted TIDCs from tumor tissue in ID8 transplanted mice with or without FASN inhibitor treatment." (PMID 30619288, 2018). "The tissue microarray results demonstrated that 9% of cases were negative for FASN expression in tumor tissues and 91% of tumors had a significant increase in FASN expression." (PMID 29872506, 2018). "We found that a progressive induction of FASN and ACLY occurred in tumor and para-tumor." (PMID 30591064, 2018). "Given that NADPH plays a major role in fatty acid synthesis by fatty acid synthase, HER-2 overexpressing tumor cells may use the PPP as a source of NADPH." (PMID 29682102, 2018). "FASN was also shown to be an upstream regulator of peroxisome proliferator-activated receptor gamma (PPAR)-β/δ in myeloid cells, and myeloid cell-specific PPAR-β/δ knockout reduced tumor burden." (PMID 30619850, 2018). "Furthermore, high levels of FASN and ACC, key proteins regulating de novo lipgenesis, were also detected in sgPten/c-Met tumor cells." (PMID 29303510, 2018). "All together, in vitro and in vivo data suggest that evaluation of FASN expression is important for selection of candidates to FASN-targeted therapy, but the tumor being positive for FASN expression is not sufficient to predict response to this therapy." (PMID 29872506, 2018). "Hence, fatty acid synthase (FASN), the enzyme responsible for de novo lipogenesis, is overexpressed in tumors including OC and is considered a useful tumor marker." (PMID 28086243, 2017). "FASN (rate‐limiting enzyme in DNL) is believed to play key roles in NAFLD progression and development and HCC; therefore, inhibiting FASN may downregulate the DNL, decrease the accumulated fat within the cells, and decrease tumor growth." (PMID 28827398, 2017). "Accordingly, ACC1 and FASN transcripts decreased in vehicle and (−)-JQ1-treated tumor-bearing mice." (PMID 29167426, 2017). "Interestingly, the serum FASN level was significantly lower in the HFD group than the LFD group and correlated inversely with tumour growth." (PMID 26878389, 2016). "This is the first study that attempt to evaluate the in vivo efficacy and feasibility of dual blockade of FASN and the HER2 signaling pathway in HER2-positive patient tumor samples (HER2-PDX) and in HER2 samples of a patient who relapsed after trastuzumab and lapatinib therapies (HER2-PDXR)." (PMID 26107737, 2015).
tumor (continued). "Furthermore, we found that combined inhibition of PI4KIIα and EGFR suppressed both PI3K/AKT and MAPK/ERK pathways, and resulted in downregulation of multiple oncogenes like PRDX2, FASN, MTA2, ultimately leading to suppression of tumor growth." (PMID 24801752, 2014). "While it appears that elevated levels of FASN are acquired during tumor progression, its exact role in tumorigenesis is not clear." (PMID 25472762, 2014). "The inhibition of the mammalian de novo synthesis of long-chain saturated fatty acids (LCFAs) by blocking the fatty acid synthase (FASN) enzyme activity in tumor cells that overexpress FASN can promote apoptosis, without apparent cytotoxic to non-tumor cells." (PMID 25255125, 2014). "Indeed, such Shh-mediated metabolic reprogramming fuels tumor progression, in an E2F1- and FASN-dependent manner." (PMID 22407012, 2012). "C75 and EGCG-treated tumours showed apoptosis by induction of PARP cleavage without any change in the total levels of FASN protein." (PMID 22769244, 2012). "FASN inhibition that blocks lipogenic pathway and impedes fatty acid synthesis, entails apoptosis in tumour cells that overexpress FASN, without affecting non-malignant cells." (PMID 22769244, 2012). "At the same time, these data suggest that, apart from FASN inhibition, ACC inhibition could also be a rational strategy to induce selective death of tumour cells." (PMID 19352381, 2009). "Tumor cells increasingly rely on de novo fatty acid synthesis, supported by key enzymes such as ATP citrate lyase (ACLY), acetyl‐CoA carboxylase (ACC1), fatty acid synthase (FASN), and stearoyl‐CoA desaturase 1 (SCD1), which together promote membrane biogenesis, signaling, and energy supply." (PMID 41163383, 2025). "Therefore, targeting against FASN with or without other molecular targeting drugs has demonstrated certain anti-tumour effect." (PMID 40414892, 2025). "Interestingly, FASN inhibition reduced tumour incidence in tg/tg mice from 80% to 0% with no tumours observed in the tg/tg colon." (PMID 40890536, 2025). "Studies assessing fatty acid synthase, enoyl-CoA hydratase short-chain 1 (ECHS1), HDL-Receptor SR-BI, the lipid transporter CD36, FA catabolic enzymes or the fatty acid transport protein 4 suggest that these genes regulate ccRCC tumor growth and can predict patient survival." (PMID 40902455, 2025). "This indicates that iCCA cells may undergo membrane formation in the absence of FASN by boosting the absorption of supplemental lipids from exogenous FAs to facilitate tumor progression." (PMID 39984452, 2025). "Additionally, enzymes like fatty acid synthase (FASN) and glucose-6-phosphate dehydrogenase (G6PD) support lipid biosynthesis and antioxidant defence, respectively, to fulfil the biochemical demands of rapidly proliferating tumours." (PMID 41154605, 2025). "Conversely, FASN knockdown enhances the ferroptosis-promoting effect of ADM, which could be reversed by Fer-1 treatment, illustrating the anti-ferroptosis effect and pro-tumor function of FASN in DLBCL." (PMID 41462004, 2025). "That ACLy and ACC knockdown strongly suppressed tumor growth whereas, the one of FASN tended, although not significantly, to reduce tumor growth may result from malonyl-CoA levels, which in addition to sustaining LCFA synthesis also inhibits their oxidation." (PMID 40822358, 2025). "Therefore, FASN inhibition is presumably helpful against some but not all tumor entities, and reliable biomarkers are needed to discriminate tumors based on their sensitivity to FASN inhibitors." (PMID 39064589, 2024). "The acetylation of FASN by lysine acetyltransferase 8 (KAT8) triggers FASN degradation through the ubiquitin‒proteasome pathway mediated by the E3 ubiquitin ligase TRIM21, leading to a reduction in de novo lipogenesis and tumor cell growth, whereas HDAC3 catalyzes FASN deacetylation." (PMID 39551780, 2024).